MIR4727 (microRNA 4727)
Synonyms: hsa-mir-4727; mir-4727
Gene: MicroRNA gene on chromosome 17 (38,825,838 to 38,825,892, forward strand). Ensembl gene ENSG00000274054.
Homologues: Orthologues: chimpanzee MIR4727 (100% identical).